APP (amyloid beta precursor protein)
Diseases named in the same sentence as APP in open-access papers (continued):
Sharing a sentence is not in itself a finding about the gene and the disease.
dementia (continued). "First, we failed to perform screening of copy number variation (deletions or duplications) in the prion protein gene (PRNP), C9ORF72 (chromosome 9 open reading frame 72), and APP, which might be responsible for a proportion of EOAD and other types of dementia." (PMID 37051054, 2023). "Low serum levels of miRNAs related to the amyloid precursor protein (APP) proteolysis, miR-20a, -27a, and -103a, were associated with significantly low cognition scores in patients who had not been diagnosed with dementia among the Japanese population." (PMID 35682821, 2022). "Some investigators believe that the lack of triplication of APP in DS patients does not trigger dementia, emphasizing the critical role of increased APP copy number in the development of AD in DS." (PMID 33638766, 2022). "In this study, the APP/PS1 double transgenic mice, which were hybridized between PRP-HAPPK595N/M596L single transgenic dementia model mice and PRP-HPS1DE9 single transgenic dementia model mice, were used as the AD model." (PMID 35019033, 2022). "Interestingly, altered PAI-1 levels have been observed in the brain of APP/PS1 mice and AD patients, being increased in correlation to age and progress of dementia." (PMID 34065168, 2021). "As in sporadic AD, Aβ seems to be the main driver of dementia in DS as indicated by case studies reporting on individuals with DS who had partial trisomy 21 but were disomic for APP and who did not develop plaques, NFTs or dementia." (PMID 34434101, 2021). "Conversely, individuals with DS (and thus APP in triplicate) show a wide range in age-of-onset of dementia, and can live into their 70s with no sign of dementia." (PMID 28993310, 2017). "Third, we did not analyze other risk factors for dementia, such as APP or presenilin (PSEN1 and PSEN2) mutations, although the prevalence of these factors in dementia is extremely low in the general population." (PMID 28144219, 2016). "It has been supported by findings that amyloid precursor protein (APP) is located on chromosome 21, which may account for the increased prevalence of dementia in older people with Down syndrome, due to a triplication of this chromosome." (PMID 25857341, 2015). "GWASs have shown that common noncoding variability in Mendelian dementia genes (APP, PSEN1, PSEN2, MAPT, GRN, and PRNP) does not influence susceptibility to AD." (PMID 25104557, 2014). "It is interesting to note that this mutation does not alter essential biological functions of APP during development, suggesting that targeting the role of Thr668, and perhaps its phosphorylation, in dementia may be an effective and safe therapeutic approach to dementias." (PMID 23451158, 2013). "Overall, these results provide genetic evidence that APP and BRI2 functionally interact and that APP mediates FDD neuropathology, and suggest that sAPPβ and/or β-CTF, rather than Aβ, are the toxic species causing dementia." (PMID 22537414, 2012). "We proved that QZZD could improve neuroinflammation and attenuate neuronal death without influencing the digestive system in APP/PS1 double transgenic mice with dementia." (PMID 36340795, 2022). "However, unlike mutations in APP and APP processing genes, mutations in MAPT typically result in in a different type of dementia called frontotemporal dementia (FTD) rather than FAD." (PMID 33255414, 2020). "Interestingly, three DS patients with partial trisomy that excludes the APP gene did not develop dementia." (PMID 32848600, 2020). "NEP and IDE levels were aberrantly decreased at the dementia stage of AD patients, but not in the preclinical stage of AD patients, and the same results were also found in the APP/PS1 mice, suggesting that Aβ-degrading activities are gradually reduced after disease onset in AD." (PMID 32256685, 2020).
dementia (continued). "The correspondence between Aβ immunoreactivity from any specific antibody, neuropathology and proposed APP cleavages is not clear and may in part explain the lack of correspondence between clinical and neuropathological diagnoses of dementia." (PMID 28126004, 2017). "The link between triplication of the APP gene and subsequent overproduction of Aβ leading to AD dementia in DS is further supported by the case of a DS individual with partial trisomy of chromosome 21 who was disomic for the APP gene and who did not develop dementia or any AD pathology." (PMID 25478025, 2014). "When it comes to the experiment, it was found that QZZD could not only alleviate impairments in spatial learning and memory, but also improve neuroinflammation and attenuate neuronal death without influencing the digestive system in APP/PS1 double transgenic mice with dementia." (PMID 36340795, 2022). "Indeed, altered APP pathways could intersect with the neurodegeneration processes of dementia, without sharing the same trajectories." (PMID 34679416, 2021). "The presence of the amyloid precursor protein (APP) gene on Hsa21 plays a role in this early onset AD, but other genes on this chromosome (e.g., RCAN1 and Dyrk1A) might also play a role in the development of AD pathology and clinical manifestations of dementia." (PMID 34501378, 2021). "The upregulation of the APP-related system in DS may explain why BACE2 SNPs are not found to be associated in general AD genome-wide association study, but are suggestive when the dementia cohort is made up of APP trisomy, as in the present study." (PMID 24462566, 2014). "In a clinical setting, we recommend to examine an extended panel of dementia genes in familial EOAD, when APP, PSEN1, and PSEN2 are tested negative, as was suggested before." (PMID 35650585, 2022). "Moreover, APOE4 may accelerate onset of dementia and neuronal degeneration by differentially impairing the maintenance of synaptic strength and reducing glutamate signaling proteins, even in the absence of overexpression of APP and Aβ APOE439." (PMID 29062035, 2017). "Rare non-DS people with duplication of APP (dupAPP) get familial early onset AD (FEOAD) with virtually 100% penetrance and prominent cerebrovascular pathology, but don't suffer from ID before dementia onset." (PMID 26648852, 2015).
Down syndrome (309 papers, 2000 to 2026). "Down syndrome is caused by trisomy of chromosome 21, on which APP is located, and is characterized by marked accumulation of Aβ fibrils in the brain." (PMID 41558820, 2026). "WMR has long been noticed to be roughly twice as common in AD as compared to normal elderly, and is reportedly pronounced relative to age-matched controls in subjects with PSEN1 and APP mutations and Down syndrome." (PMID 39656832, 2025). "We examined TMCC2 immunoreactivity in late onset AD cases stratified by APOE genotype and age‐matched non‐demented controls, as well as in early onset AD cases associated with mutations in APP or Down syndrome." (PMID 39084860, 2025). "Due to the dose-sensitive role of the amyloid precursor protein (APP) gene, located on chromosome 21 (Chr21), people with Down Syndrome (DS) face an increased risk of developing early-onset AD (EOAD)." (PMID 41551612, 2025). "The result seems paradoxical given that over dosage of APP gene in Down syndrome is linked to early-onset AD." (PMID 40050982, 2025). "For example, Down’s syndrome (DS) is caused by trisomy of human chromosome 21, where the AD risk gene (amyloid precursor protein or APP) resides." (PMID 39596399, 2024). "In individuals with Down syndrome (DS), trisomy of chromosome 21 amplifies the expression of the APP gene, causing increased APP processing and Aβ overproduction, which subsequently accumulates." (PMID 38940611, 2024). "In summary, their results highlight the potential of APP ASOs as a therapeutic approach for forms of AD caused by duplication of the APP gene, including monogenic AD and Down syndrome-related AD." (PMID 39075597, 2024). "Down syndrome, with three alleles of APP and a resulting over-production of Aβ product, represents another at-risk group for genetic AD." (PMID 39322953, 2024). "The most salient support of ACH is the abnormal cleavage of APP protein and the increased production of Aβ in the ADAD due to mutations in APP, PS1, or PS2, or in Down syndrome due to the three alleles of APP." (PMID 38256670, 2024). "The APP gene is located on chromosome 21, and the extra copy of APP causes the overproduction of Aβ in Down’s syndrome patients, resulting in a young-onset AD phenotype." (PMID 38245771, 2024). "Our results highlight the potential of APP ASOs as a therapeutic approach for forms of AD caused by duplication of the APP gene, including monogenic AD and AD related to Down syndrome." (PMID 38527856, 2024). "The gene encoding the amyloid precursor protein (APP) was identified on chromosome 21, which corresponded with Down’s syndrome individuals who consistently exhibited AD." (PMID 34983641, 2022). "Findings of different segmental duplications of chromosome 21 subregions in Down’s syndrome conclusively show that lifelong overexpression of wild-type APP causes AD." (PMID 35865745, 2022). "Down syndrome individual has trisomy on chromosome 21, and an extra copy of APP causes overproduction of Aβ due to increased APP expression by proteolytic processing." (PMID 36361714, 2022). "Here, we have a second example, beside the triplication of APP in Down syndrome, where simple overproduction of Aβ is causative of AD." (PMID 35862308, 2022). "Age at onset spanned 36 years in families with the 3.4Mb APP duplication, 34 years in the APP V717I variant, 32 years in Down syndrome, 33 years in the E280A PSEN1 variant, and 29 years in the PSEN2 N141I variant." (PMID 35604690, 2022). "If increased Aβ production, as observed in patients with Down syndrome or the Swedish APP mutation, drives AD pathogenesis, what about reduced Aβ production?" (PMID 35862308, 2022). "Down’s syndrome (DS) is an aneuploidy due to triplication of all or part of chromosome 21, where the amyloid precursor protein (APP) gene is encoded, and plays a key role in the pathogenesis of AD dementia in DS." (PMID 33994996, 2021).
Down syndrome (continued). "The progression of pathological changes characteristic for AD associated with triplication of the APP gene and the disorders accompanying Down’s syndrome, require deeply thought decisions concerning pharmacotherapy and care." (PMID 34121170, 2021). "Copy number studies in AD have focused largely on chromosome 21 and the APP locus specifically, because germline trisomy 21 (Down’s syndrome) increases the lifetime risk of AD, largely through APP overexpression." (PMID 33979534, 2021). "The APP gene is found on chromosome 21 and Trisomy 21 carriers (Down’s syndrome) have a high frequency of early onset AD, presumably caused by an increased dosage of APP." (PMID 34884970, 2021). "Such mutations include amyloid precursor protein (APP) gene duplication in Down syndrome and synuclein gene (SNCA) duplication in familial PD, both leading to early AD and PD pathologies, respectively." (PMID 32372895, 2020). "This is interesting as individuals with Down syndrome often develop AD as a result of trisomy of chromosome 21, causing them to have an additional copy of the amyloid precursor protein (APP) gene." (PMID 32745807, 2020). "The progress in the study of AD and the early identification of amyloid deposit in AD and Down syndrome led to the identification of an association between APP gene and Aβ peptide in CAA." (PMID 32414028, 2020). "Based on the increased prevalence of early onset AD (EOAD) in Down syndrome patients with three copies of the APP gene and in people with the APP gain of function mutation that increases Aβ levels, Aβ has been thought to be a major cause of AD." (PMID 32019113, 2020). "Down Syndrome (DS), the most common cause of genetic intellectual disability, is characterized by over-expression of the APP and DYRK1A genes, located on the triplicated chromosome 21." (PMID 30389461, 2019). "Abnormal Aβ accumulation has also been reported in iPSC-derived neurons from AD patients carrying APP V717I mutation, duplicated APP, as well as those with Down syndrome." (PMID 30238389, 2019). "The APP gene is located on chromosome 21, and its presence in three copies in Down syndrome is presumed to underlie the development of early-onset AD in this population." (PMID 31788001, 2019). "It is well-known that APP gene mutations, duplication of its gene or trisomy of chromosome 21 (Down’s syndrome) cause fAD." (PMID 30542277, 2018). "In further support of these findings, we found that elevation of APP was associated with a decreased BACE1-mediated processing of CHL1 in human brains from subjects affected by Down syndrome." (PMID 29391027, 2018). "Down syndrome [resulting in an extra copy of the gene coding for the amyloid precursor protein (APP) located in chromosome 21], which is associated with increased incidence and earlier onset of AD, lent further support to the ACH." (PMID 28424614, 2017). "Consistently, overexpression of wild-type hAPP causes early onset familial AD in human carriers with APP duplications and presumably in Down’s syndrome." (PMID 28750656, 2017). "The overexpression of APP, a hallmark of Down syndrome, is known to be associated with oxidative stress." (PMID 26848775, 2016). "The APP gene is located on chromosome 21, and trisomy of this chromosome is associated with Down’s syndrome, which exhibits an AD-like pathology." (PMID 25869641, 2015). "This change in Aβ can arise from heightened APP levels due to mutations in APP or from increased APP copy number as observed in Down’s syndrome (Trisomy 21)." (PMID 26618502, 2015). "Another line of evidence is that humans with Down syndrome develop similar pathological changes as a result of the triplication of chromosome 21, on which the amyloid precursor protein (APP) is encoded." (PMID 26063233, 2015). "Triplication of the APP gene, which is localized on chromosome 21, is the cause of this greater predisposition of early onset of AD pathology in patients with Down syndrome." (PMID 26041981, 2015).
Down syndrome (continued). "The highly conserved APP gene is located on chromosome 21 and overexpression of APP in Down’s syndrome (trisomy 21) causes accumulation of amyloid plaques early in life." (PMID 25862638, 2015). "First, Down syndrome (DS), with three copies of APP, produces neuropathology virtually identical to AD and APP locus duplications are sufficient to cause familial AD." (PMID 25650802, 2015). "In animal models of Down syndrome, which are trisomic for the APP gene locus and thus overexpress APP, spine loss and synaptic damage have been described." (PMID 26063233, 2015). "Early onset AD also occurs in individuals with a duplication of the APP locus, a rare cause of FAD, and in individuals with Trisomy 21/Down syndrome, suggesting that increasing APP dosage is sufficient for disease initiation." (PMID 24939911, 2014). "Down Syndrome (DS) is caused by trisomy of chromosome 21, which includes the gene for the amyloid precursor protein (APP) and leads to overproduction of beta-amyloid." (PMID 25478025, 2014). "The trisomy mutation associated with Down’s syndrome also increases Aβ accumulation leading to early AD pathology and is considered to be caused by the increased copy number of APP that lies within chromosome 21." (PMID 24795635, 2014). "Down syndrome (DS) is a common neurodevelopmental condition most frequently caused by trisomy of chromosome 21, on which the APP gene resides." (PMID 25217249, 2014). "Later it was discovered that mutations in the APP gene, or increased copy number of APP found in Down's syndrome are associated with early onset AD pathology." (PMID 25191216, 2014). "Our data evidenced a novel therapeutic strategy of potential impact for people with trisomy of the APP gene on chromosome 21, which is a phenotype long associated with Down syndrome (DS) that can also cause familial Alzheimer's disease." (PMID 23935819, 2013). "We investigated the potential pathogenic role of secretion of flAPP and APP-CTFs via the exosome secretory pathway, in vivo in the brain of Down's syndrome patients." (PMID 26082317, 2013). "The association between AD and Down's syndrome has long been known, providing evidence that a higher gene dosage of APP is sufficient to produce an AD phenotype." (PMID 21193246, 2012). "An extra copy of the APP gene is duplicated along with the other chromosome 21 genes in Down's syndrome, which further implicated the APP gene in Alzheimer's pathology." (PMID 24278680, 2012). "A chimeric mouse model of Down syndrome shows increased APP transcription associated with cholinergic neuron degeneration." (PMID 20205906, 2010). "In Down syndrome, trisomy of chromosome 21 leads to the overproduction of the APP gene and causes increased levels of amyloid-beta peptides and phosphorylated tau protein, which ultimately facilitates the formation of amyloid plaques and neurofibrillary tangles." (PMID 41465426, 2025). "Additionally, Down Syndrome is regarded as a further risk factor for AD development due to the location of the APP gene on chromosome 21." (PMID 40725224, 2025). "Studies show that up to 90% of individuals with Down syndrome after the age of 65 display pathological signs of Alzheimer’s, which is caused by trisomy of chromosome 21 and the overexpression of the amyloid precursor protein (APP) gene." (PMID 41465426, 2025). "Dysregulation of endocytosis in Down syndrome has been linked to an increased dose of several endosomal pathway-related genes that map to chromosome 21, such as amyloid precursor protein (APP), synaptojanin-1 (SYNJ1), intersectin-1 (ITSN1), and regulator of calcineurin 1 (RCAN1)." (PMID 38540156, 2024). "Chromosome 21 trisomy, the presence of APP on chromosome 21, and association of APP gene upregulation with increased risk of hematologic malignancy in patients with Down syndrome (DS) suggest that APP might predispose to cancer." (PMID 37383425, 2023).